RNU6-1232P (RNA, U6 small nuclear 1232, pseudogene)
Gene: Small nuclear RNA gene on chromosome 5 (68,159,061 to 68,159,146, reverse strand). Ensembl gene ENSG00000252108.
Homologues: Orthologues: chimpanzee U6 (99% identical), macaque U6 (90% identical), dog U6 (76% identical), rabbit U6 (76% identical), dog U6 (74% identical). Paralogues in human: RNU6-672P (88% identical), RNU6-44P (87% identical), RNU6-637P (87% identical), RNU6-657P (87% identical), RNU6-140P (86% identical), RNU6-145P (86% identical), RNU6-41P (86% identical), RNU6-1029P (85% identical), RNU6-1060P (85% identical), RNU6-1117P (85% identical), RNU6-1122P (85% identical), RNU6-116P (85% identical), and 1288 more.